GSK3B (glycogen synthase kinase 3 beta)
Diseases named in the same sentence as GSK3B in open-access papers (continued):
Sharing a sentence is not in itself a finding about the gene and the disease.
breast cancer (continued). "To further investigate the function of GSK3B in breast cancer, we performed immunohistochemical staining on breast cancer tissues and adjacent normal tissues." (PMID 30181805, 2018). "In normal endometrium and in breast cancer cell lines, GSK3β is typically inactivated by the oestrogen receptor-AKT pathway." (PMID 29724995, 2018). "There are 7 genes in this subnetwork, of which three genes (“GSK3B”, “CTNNB1”, “PIK3CA”) are associated with breast cancer." (PMID 30598085, 2018). "In the current study, the antitumor mechanism of Moracin D, a constituent of Morus alba, was examined in breast cancer cells in association with FOXM1 and β-Catenin/GSK3β signaling." (PMID 30201862, 2018). "For example, activation of GSK3β induces apoptosis, accumulation of β-catenin and suppression of Cyclin D1 expression in human breast cancer cells." (PMID 29700285, 2018). "Recent evidence indicates that GSK3β acts as a tumor suppressor gene and that its expression is continually depleted in many human cancers including breast cancer, prostate cancer, and colorectal cancer." (PMID 30253791, 2018). "Antrocin has been demonstrated to be a small-molecule inhibitor of AKT/mTOR/GSK-3β/NF-κB signaling in metastatic breast cancer cells." (PMID 30602706, 2018). "GSK3β has been proposed to be involved in breast cancer cell metastasis via regulation of Snail1 activity." (PMID 29700285, 2018). "Cross-cancer alteration analysis showed that GSK3B has an amplification pattern in most cancer types, especially in breast cancer." (PMID 30181805, 2018). "In colorectal and breast cancer, Rab3D has been reported to promote metastasis through activating Akt/GSK3β/Snail pathway and inducing epithelial mesenchymal transition (EMT) process." (PMID 29423086, 2018). "Preclinical in vivo and in vitro breast cancer models have shown that PARP inhibition can upregulate PD-L1 by inactivating GSK3β, and that subsequent blockade of PD-L1 resensitizes PARP inhibitor-treated cells to T-cell killing." (PMID 30514390, 2018). "Together, our results show that TP53INP1 inhibits hypoxia‐induced EMT and VM formation via the ROS/GSK‐3β/Snail pathway in breast cancer, which offers new insights into breast cancer clinical therapy." (PMID 29655255, 2018). "Recent evidence has indicated that glycogen synthase kinase 3 beta (GSK3β) positively regulates mTORC1 activity in MCF-7 breast cancer cells." (PMID 29162840, 2017). "Previous studies suggest that Slug phosphorylated by GSK3β undergoes ubiquitination and proteosomal degradation in breast cancer 23 and non‐small cell lung cancer." (PMID 27878953, 2017). "Taken together our results supported that ALX4 inhibited the progression of breast cancer through interfering Wnt/β-catenin signaling via promoting phosphorylation degradation of β-catenin in a GSK3β dependent manner." (PMID 29183346, 2017). "SYNJ2BP was able to directly regulate GSK3β phosphorylation by influencing the PI3K/AKT pathway to enhance breast cancer cell metastasis." (PMID 29163781, 2017). "VEGF-A is reported to be an inducer of EMT through enhancing Snail expression in breast cancer cells, partly by inhibiting GSK3β activity." (PMID 27901498, 2017). "It was previously reported that RPN2-knockdown promoted GSK3β-mediated suppression of heat shock proteins (HSP) in human breast cancer cells." (PMID 29069815, 2017). "As revealed in our previous studies performed in breast cancer cells, G-1 can also suppress the activity of NF-κB in CRC cells via increasing the phosphorylation of GSK-3β and its association with p65." (PMID 28476123, 2017). "Other reports show that GSK-3β activation enhances and sensitizes human breast cancer cells to paclitaxel, 5-fluorouracil, cisplatin, taxol and prodigiosin." (PMID 27123999, 2016). "In summary, we firstly demonstrates that miR-3646 contributes to drug resistance of breast cancer cells to Doc at least in part through activation of GSK-3β/β-catenin pathway by suppressing expression of GSK-3β." (PMID 27045586, 2016).
breast cancer (continued). "We demonstrate CCL5-inducible rapid activation of the mTOR/AKT pathway as well as phosphorylation of a downstream substrate, GSK3β, in breast cancer cells." (PMID 27335323, 2016). "Inactivation of GSK3β as measured by its phosphorylation at Ser9 is positively correlated with higher level of H3K27 trimethylation in tumor tissues from breast cancer patients." (PMID 27494834, 2016). "Here, the authors show that in breast cancer, PD-L1 expression can be up regulated post-translationally by glycosylation, which in turn acts through inhibiting GSK3β-mediated PD-L1 degradation." (PMID 27572267, 2016). "It had been demonstrated that overexpression of versican by G3 domain-containing EGF-like motifs enhanced breast cancer self-renewal through EGFR/AKT/GSK3β signaling, and increased resistance to chemotherapy." (PMID 27490467, 2016). "Previous studies reported that CCL18-PITPNM3 binding induces Pyk2/Src or PI3K/Akt/GSK3β/Snail signaling and the subsequent metastasis of breast cancer." (PMID 26919103, 2016). "In breast cancer cells, GSK3β suppresses epithelial-mesenchymal transition by control of Snail stabilization." (PMID 27494834, 2016). "Together with previously published reports, our results further strengthened the role of GSK3β as a tumor suppressor in breast cancer and implied that inactivation of GSK3β is one of the mechanisms enhancing EZH2 activity in cancer." (PMID 27494834, 2016). "Erk and GSK3β phosphorylation levels were decreased in the breast cancer cells when treated with the drugs." (PMID 27270654, 2016). "Previous studies have shown that GSK-3β overexpression plays key roles in multiple types of cancer, including ovarian cancer, breast cancer, pancreatic cancer, colon cancer, bladder cancer, myeloma and leukaemia." (PMID 27588482, 2016). "There is evidence that GSK3β functions as a tumor suppressor in skin and breast cancer and that repression of RNA polymerase 1 transcription by GSK3β contributes to this tumor suppressor action." (PMID 27087918, 2016). "We observed that both compounds readily induced BRG1 as well as reduced GSK3β phosphorylation, and inhibited the growth of Sum159 and DT13, two BRG1- deficient breast cancer cell lines." (PMID 28105458, 2016). "As an identical candidate, miR-3646 has been shown to be an important regulator responsible to Doc-resistant phenotype of breast cancer cells, and manipulates GSK-3β-dependent activation of β-catenin signaling pathway." (PMID 27045586, 2016). "GSK‐3β is proved to direct proliferation of breast cancer cells interplayed with histone H3 phosphorylation and DNA methylation." (PMID 27060477, 2016). "Consistently, the immunohistochemical staining results revealed that inactivation of GSK3β is significantly correlated with higher level of H3K27 trimethylation in breast cancer patients." (PMID 27494834, 2016). "We also demonstrate that epidermal growth factor (EGF) stabilizes PD-L1 via GSK3β inactivation in basal-like breast cancer." (PMID 27572267, 2016). "MiR-1229 upregulation drastically promoted breast cancer cell proliferation by inhibiting the expression of three key negative regulators (GSK-3β, APC, and ICAT) of the Wnt/β-catenin signaling pathway." (PMID 26992223, 2016). "MiR-1229 upregulation promoted cell proliferation in breast cancer both in vitro and in vivo, and activated Wnt/β-catenin signaling by directly targeting GSK-3β, APC, and inhibitor of β-catenin and T cell factor (ICAT)." (PMID 26992223, 2016). "An in vitro study revealed that down-regulation of SAM68 in breast cancer cells inhibited cell proliferation by blocking the transition from G1 to S phase, and the Akt/GSK-3β signaling and FOXO/p21/p27 pathway appeared to be involved." (PMID 25944080, 2015). "NFAT1 also functions as a critical factor in Akt/protein kinase B (PKB) and Glycogen synthase kinase 3β (GSK3β) signaling pathways to regulate the breast cancer metastasis." (PMID 26461225, 2015).
breast cancer (continued). "We have also recently demonstrated that RPN2 regulates cancer stem cell properties through the functional suppression of glycogen synthase kinase 3β (GSK3β) in breast cancer cells." (PMID 25595901, 2015). "A previous study revealed that AKT/GSK-3β pathway activation plays an important role in cisplatin resistance of breast cancer." (PMID 24944676, 2014). "Phosphorylation mediated suppression of GSK3β promotes breast tumor initiation and metastasis, and reduced phosphorylation of GSK3β efficiently inhibit cancer stem cell-like phenotypes in breast cancer." (PMID 24886245, 2014). "The rapid estrogen signaling via the AKT/GSK3β pathway is involved in estrogen-stimulated growth of ER-positive breast cancer stem/progenitor cells." (PMID 24558373, 2014). "In oral, laryngeal, esophageal and salivary gland cancer, breast cancer phosphorylation on the inhibitory serine (GSK3β S9) was reported to be elevated and the activity of GSK3 was reasoned to be reduced as a result." (PMID 25486534, 2014). "GSK3β acts as a mediator of rapamycin-induced growth inhibition: rapamycin treatment increases the activity of GSK3β and downregulates cyclin D1 levels in a GSK3β-dependent fashion in human breast cancer cell lines." (PMID 24995926, 2014). "We found that estrogen induced the activation of the PI3K/AKT/GSK3β/β-catenin signaling pathway in ER-positive breast cancer stem/progenitor cells, which was attenuated by the AKT inhibitor." (PMID 24558373, 2014). "Our data clearly shows inhibition of ILK1, paxillin, Akt, ERK and Rho kinases while inducing GSK3β by CuB treatment in breast cancer cells." (PMID 24729020, 2014). "Our results thus indicated that the PI3K/AKT/GSK3β/β-catenin signaling pathway is involved in ER-α36-mediated mitogenic estrogen signaling of ER-positive breast cancer stem/progenitor cells." (PMID 24558373, 2014). "It has been reported that inactivation of GSK3β indicated by increased p-GSK3β was found in approximately half of the invasive mammary carcinomas, and significantly correlated with a worse clinical outcome." (PMID 24886245, 2014). "In contrast, Gadd45a functions to promote Myc-driven breast cancer by negatively regulating MMP10 via GSK3B/B-catenin signaling, resulting in increased tumor vascularization and growth." (PMID 23706118, 2013). "GSK3β inactivation through AKT hyperactivation was shown to increase anti-apoptotic Mcl-1 protein levels in breast cancer." (PMID 23565238, 2013). "APN treatment of MDA-MB-231 breast cancer cells inhibits the phosphorylation of GSK3β, resulting in the degradation of β-catenin and subsequently causes the decrease of cyclin D1 expression." (PMID 23691481, 2012). "In breast cancer (where active GSK3β acts like a tumor suppressor as in OSCC) knock down of PI3K promotes degradation of FH and p27 possibly via GSK3β activation." (PMID 20537194, 2010). "GSK-3β expression has been correlated with a favorable outcome in squamous cell carcinoma of the tongue and breast cancer." (PMID 20704706, 2010). "Activated GSK-3β has been shown to inhibit cyclin D1 expression in tumor cells including breast cancer cells and squamous cancer cells of the tongue." (PMID 20704706, 2010). "Taken together, these findings demonstrate that rapamycin activates GSK3β and induces the phosphorylation dependent degradation of cyclin D1 via the ubiquitin pathway in breast cancer cell lines." (PMID 17407548, 2007). "Our findings identify GSK3β as an important mediator of TSA-induced cytotoxicity in MCF-7 breast cancer cells." (PMID 17018141, 2006). "Our findings identify GSK3β as an important mediator of TSA-induced apopotosis in MCF-7 breast cancer cells." (PMID 17018141, 2006). "In the present study, we investigated the role of GSK3β in mediating cytotoxicity in MCF-7 breast cancer cells treated with trichostatin A (TSA), a prototype HDACI." (PMID 17018141, 2006).
breast cancer (continued). "In the present study, we investigated the role of GSK3β in mediating the cytotoxic effects in MCF-7 breast cancer cells treated with trichostatin A (TSA), a prototype HDACI." (PMID 17018141, 2006). "GSK3-β is involved in the regulation of protein synthesis, cell proliferation, cell differentiation, neuronal signaling, immune function, and inflammation, and has been found to be upregulated in several cancers, including breast cancer." (PMID 41009395, 2025). "Additionally, we observed that SGK3 promoted tumor cell stemness by activating GSK3β/β-catenin signaling pathway, leading to the resistance to alpelisib in breast cancer." (PMID 40303291, 2025). "We therefore investigated whether the application of incremental solid stress would activate the Akt/GSK-3β signalling pathway in an incremental manner in breast cancer cells." (PMID 40371393, 2025). "In breast cancer, inhibiting overexpression of GSK3B can also overcome chemoresistance." (PMID 38814517, 2024). "High GSK3β expression is reported to be correlated with worse breast cancer and CRC outcomes." (PMID 39518976, 2024). "Similarly, the MyD88 inhibitor TJ-M2010-2 suppresses the proliferation, migration, and invasion of breast cancer cells by intervening in the MyD88/GSK-3β and MyD88/NF-κB signaling pathways." (PMID 38347830, 2024). "In breast cancer, loss of SLIT/ROBO signaling may decrease the phosphorylation of downstream CXCL12/CXCR4 molecules, increase GSK-3β phosphorylation, and influence the expression and distribution of β-catenin." (PMID 39479352, 2024). "In addition, NOTCH3 up-regulates the expression of GSK3β, which is related to better recurrence-free survival rate of all breast cancer patients." (PMID 38164285, 2024). "Meanwhile, the phosphorylation of AKT, mediated by GSK-3β and PTEN, is associated with cell viability, migration, and apoptosis, which may promote chemotherapy resistance in breast cancer." (PMID 39769140, 2024). "Overexpression of GSK-3β in TNBC cells can inhibit Nrf2 expression, increase ROS and MDA levels, enhance erastin-induced ferroptosis, and in an in vivo breast cancer xenograft model, GSK-3β overexpression enhances the tumor growth-inhibiting effect induced by erastin." (PMID 39664391, 2024). "In vitro studies have demonstrated that whey protein concentrate (WPC) enhances the antioxidant capacity of cancer cells and induces sensitivity to rapamycin through modulation the cellular redox state and activating GSK3β/mTORC1 signaling in MDA-MB-231 breast cancer cells." (PMID 38594256, 2024). "Additionally, our rescue experiments demonstrated that the mechanism by which FATS regulates breast cancer sensitivity to paclitaxel chemotherapy is also achieved through the MYH9/GSK3β/β-catenin axis." (PMID 39550407, 2024). "In the present work, we observed that GSK3B knockdown and the CP21R7 treatment significantly increased the protein level of the epithelial marker E-cadherin, which is in line with a previous finding that GSK3B inhibition stabilized E-cadherin expression in breast cancer." (PMID 39166606, 2024). "In addition, several disease pathways including the ‘endometrial cancer, ‘colorectal cancer’, ‘ErbB signaling’, ‘breast cancer’, and ‘gastric cancer’ pathways with Kras, Gsk3b, and Raf1 genes were significantly enriched." (PMID 37505851, 2023). "This indicates that GSK-3β is a tumor suppressor in breast cancer." (PMID 36671478, 2023). "In view of the fact that adiponectin inhibits proliferation through blocking phosphorylation of GSK-3β, preventing β-catenin activation, and nuclear translocalization in breast cancer, this effect has been investigated on GSK-3β signaling pathways in RCC cells." (PMID 37686525, 2023). "The stabilization of PRLR is also mediated by the human epidermal growth factor receptor 2 (HER2)-/RAS-signaling-induced inhibitory phosphorylation of GSK3β in breast cancer cells, and elevated PRLR levels are correlated with GSK3β inactivation in breast cancer specimens." (PMID 37686524, 2023).
breast cancer (continued). "Recent findings show that PI3K signaling enhances Wnt/β-catenin signaling in ER+ breast cancer by promoting GSK3β lysosomal degradation, but paradoxically suppresses Wnt/β-catenin activation in ER− breast cancer by unknown mechanisms." (PMID 37471270, 2023). "Knockdown of GSK3β in breast cancer cells has been shown to inhibit cellular proliferation." (PMID 37259304, 2023). "Remarkably, this finding demonstrates for the first time that Notch3 may inhibit the EMT process in breast cancer cells through transcriptionally upregulating GSK3β." (PMID 36139447, 2022). "The suppression of Notch3 expression may contribute to EMT by transcriptionally downregulating GSK3β in breast cancer." (PMID 36139447, 2022). "In summary, our preliminary results suggested that Notch3 might inhibit EMT by trans-activating GSK3β in breast cancer cells." (PMID 36139447, 2022). "GSK3β reportedly stimulates the development of certain tumors, including those in pancreatic cancer, colorectal cancer and myeloma cancer, while inhibiting the development of other tumors, including those in lung, esophageal, and breast cancer." (PMID 35265070, 2022). "In breast cancer, overexpression of GSK-3β enhances erastin-induced ferroptosis." (PMID 35350242, 2022). "The purpose of this study was to investigate whether Notch3 acts as a transcriptional activator of GSK3β in breast cancer." (PMID 36139447, 2022). "We investigated whether crosstalk existed between Notch3 and GSK3β in the progression of EMT in breast cancer." (PMID 36139447, 2022). "In addition, GSK3β has been found to exhibit a key role in the development of human cancers such as breast cancer, colorectal cancer, and PC." (PMID 35999213, 2022). "In addition, hinokitiol activates the AKT/GSK-3β/β-catenin signaling cascade to inhibit the growth of ER-negative MCF10DCIS.com human breast cancer cells." (PMID 34361036, 2021). "Moreover, β-catenin/T-cell factor (TCF) transcriptional complex regulates Snail1 via Axin2-mediated nuclear export of GSK-3β in breast cancer." (PMID 34917071, 2021). "We also found that the n-hexane fraction could inhibit the Wnt/β-catenin signaling via GSK-3β in breast cancer cells." (PMID 33746192, 2021). "GSK3β inactivation stabilizes β-catenin expression, induces its translocation to the nucleus, upregulates the downstream target CCND1 gene (encoding cyclin D1), and promotes breast cancer stem cell (BCSC) function and mammary tumor development." (PMID 34403222, 2021). "In summary, our study demonstrated a critical role of PPA1 in mediating PI3K/AKT/GSK3β signaling-induced tumor progression, which could be a useful target to prevent breast cancer." (PMID 34595179, 2021). "PGK1-coupled HSP90 may stabilize GSK3β expression to modulate the stemness features in breast cancer." (PMID 34790279, 2021). "Similar to melanoma, previous research suggested that GSK-3β may function as a tumor suppressor for breast cancer." (PMID 34966427, 2021). "In addition, immunoblotting showed that Hsp90 depletion significantly reduced GSK3β expression in MCF-7ADR human breast cancer cells." (PMID 34403222, 2021). "To further investigate the mechanism underlying the regulatory effects of PPA1 on breast cancer progression and EMT, we first performed western blot and the results demonstrated that silencing PPA1 restrained the phosphorylation levels of PI3K, AKT, and GSK3β." (PMID 34595179, 2021). "We have shown that inhibition of GSK-3β activity may increase the drug-resistance of breast cancer cells to certain chemotherapeutic drugs." (PMID 33917370, 2021). "The serine/threonine protein kinases CDK2 and GSK-3β are key oncotargets in breast cancer cell lines, therefore, in the present study three series of oxindole-benzofuran hybrids were designed and synthesised as dual CDK2/GSK-3β inhibitors targeting breast cancer (5a–g, 7a–h, and 13a–b)." (PMID 33327806, 2021).